SRSF2 (serine and arginine rich splicing factor 2)
Diseases named in the same sentence as SRSF2 in open-access papers (continued):
Sharing a sentence is not in itself a finding about the gene and the disease.
tumor (continued). "Interestingly, we found several tumor suppressor miRNAs to be downregulated in patient samples with SF3B1 and SRSF2 mutations." (PMID 26848861, 2016). "Furthermore, according to qPCR analysis, the mean expression of SRSF2 mRNA was moderately decreased (p = 0.0005) in ccRCC tumour samples when compared with controls." (PMID 27690003, 2016). "Since regulation of SRSF2 involved acetyltransferase Tip60, and kinases SRPK1 and SRPK2, it is conceivable to speculate that in most tumor cells the regulation of SRSF2 was disturbed." (PMID 22957056, 2012). "Therefore, tumor SRSF2 expression levels should be considered when selecting appropriate mAbs." (PMID 41228255, 2025). "Therefore, it would be informative to test whether inhibition of Igf2 signaling could suppress tumor formation in the Srsf2 HKO mice model in the future." (PMID 32372053, 2020). "The participants with a) the SF3B1 p.K666N and b) SRSF2 p.P95L/TET2 p.I1873T variants, respectively, both had haematological malignancies diagnosed in a closer timeframe after blood draw (exact date unknown) and therefore, tumour cells may have been detected." (PMID 29641532, 2018). "By reducing the acetylation level of SRSF2 protein and activating HDAC10, Sono@NAT10 promotes M1 polarization, suppresses tumor progression, and strengthens immunotherapy." (PMID 41144699, 2026). "Consistently, Western blot results demonstrated that, relative to the PBS, CuZCeP@NC, and Sono@NC groups, tumor tissues from the Sono@NAT10 group exhibited significantly lower NAT10 and SRSF2 expression, accompanied by a notable upregulation of HDAC10." (PMID 41144699, 2026). "While there is no recurrent gene amplification that was observed, the following genes were amplified in two tumor samples: MET, SMO, ERBB2, BRAF, EZH2, SRSF2, CUX1, and CEBPA." (PMID 38164123, 2024). "As expected, the SRSFs with CNV amplification displayed significantly higher expression in tumor tissues compared to normal ones (e.g., SRSF1, SRSF2, SRSF3, and SRSF6)." (PMID 38015716, 2023). "Besides, we selected 5 key genes (SRSF2, HELLS, PNN, TK1, and CKS2) in hallmark_E2F_targets in Pathcards database and validated that they are associated with overall survival, metastasis, and tumor stage of patients with PCa through multiple online database validation." (PMID 35392496, 2022). "SRSF2 knockdown resulted in decreased MBD2_v2 expression, decreased CSCs in TNBC cell cultures, and hindered tumor formation in vivo." (PMID 30636104, 2019). "We present new mechanistic evidence that ROS‐dependent expression of SRSF2 drives TNBC MBD2_v2 expression and tumor‐initiating CSCs." (PMID 30636104, 2019). "Mutations in various splicing regulatory factors such as U2AF1, ZRSR2, SRSF2, SF3B1, and RBM10 have been described in multiple tumor types." (PMID 28105922, 2016). "For example, miR-193a-3p was shown to promote in vivo tumorigenesis of metastatic medullary thyroid carcinoma, and to enhance both tumor growth in nude mice and chemoresistance of HCC by targeting of the SRSF2 gene." (PMID 25311867, 2014). "We previously reported significant elevation of pathway genes TET1, TARDBP, and SRSF2 in TNBC tumor samples obtained from obese (BMI > 30) compared to non-obese (BMI < 30) patients, as measured by qRT-PCR." (PMID 37231419, 2023). "SRSF2 IHC assays confirmed the increased protein expression of SRSF2 in CRC tumor tissues compared with the nontumor adjacent tissues." (PMID 36623729, 2023). "Compared with the control group, we observed a significant decrease in both tumor growth rate and tumor weight in SRSF2 knockdown groups, while there was no significance in the body weight between the two groups of mice." (PMID 36623729, 2023). "To uncover the mechanism by which SRSF2 regulates the immune response of autologous TILs, we first used a RCC data set (GSE40435) from the National Center for Biotechnology Information (NCBI) database to analyze SRSF2 expression levels in the RCC tumor tissue and adjacent tumor tissue." (PMID 31838573, 2020).
tumor (continued). "SRSF2 knockdown cells demonstrated significantly delayed tumor initiation relative to nonsilencing control cells (P < 0.05)." (PMID 30636104, 2019). "Using tissue samples obtained from ccRCC patients, as well as independent validation on The Cancer Genome Atlas (TCGA) data, we demonstrate for the first time that expression of SRSF2 is decreased in ccRCC tumours when compared to non-tumorous control tissues." (PMID 27690003, 2016). "SRSF2 mRNA expression was decreased in tumour samples by 1.68-fold when compared with non-tumourous control samples (p = 1.23 × 10−18)." (PMID 27690003, 2016). "Furthermore, the precise significance of the splice factor SRSF2 for the survival of tumor patients with or without therapeutic PD-L1 antibody treatment was characterized." (PMID 41228255, 2025). "However, due to the limited number of human CRC samples that we collected from the hospital among which there were rare patients with tumor grade I or IV, we did not observe a significant relationship between SRSF2 mRNA levels and clinicopathological features." (PMID 36623729, 2023). "Furthermore, SRSF2 and 3 showed the strongest correlation with PRMT5 in LIHC tumor specimens." (PMID 36499164, 2022). "Taken together, our results show that most TILs isolated from primary RCC specimens could not recognize autologous tumor cells and that SRSF2 functions as an important regulator of the immune response against tumor cells in TILs." (PMID 31838573, 2020). "In addition, no tumors were detected in the Srsf2−/− mice following 11 months of polyI:C treatment, suggesting the requirement of chronic and extensive injury during the tumor development." (PMID 32372053, 2020). "In this study, we found that tumor cells isolated from RCC tissue did not trigger the immune response of TILs and downregulation of SRSF2 in these TILs could significantly improve their immune response against tumor cells." (PMID 31838573, 2020).
hematological malignancies (18 papers, 2019 to 2025). "For example, the gene for SR protein SRSF2 (also called SC35), required for both alternative and constitutive splicing, has been found to be mutated in some hematological malignancies and associated with the mis-splicing of many pre-mRNAs." (PMID 36979496, 2023). "Relationship between AKT3 and mutations related to MDS or MPN hematological disorders The MDS- or MPN-related mutations affect genes involved in different molecular aspects of gene expression including RNA splicing (SRSF2, U2AF1 and SF3B1), chromatin remodeling (ASXL1) and gene transcription (BCOR)." (PMID 38528080, 2024). "To validate our findings, we analyzed the splicing landscape and expression profiles of key splicing machinery genes, including SRSF2, U2AF1, and ZRSR2, which are known to be frequently mutated in hematological malignancies." (PMID 40158006, 2025). "The most significantly hypermethylated CpGs were frequently linked to genes involved in the pathogenesis of hematological diseases, including RUNX1, BRD4, SRSF2, SETBP1 and TNFSF10." (PMID 40319310, 2025). "Mutations in splicing factors, such as U2AF1, SF3B1, SRSF2, ZRSR2, and HNRNPH1, are frequently observed across various hematological malignancies and are associated with poor prognosis and treatment resistance." (PMID 39584923, 2024). "Along with SF3B1 mutations, recurrent missense mutations in U2 small nuclear RNA auxiliary factor 1 (U2AF1) and serine/arginine-rich splicing factor 2 (SRSF2) were discovered in hematological malignancies, and later reported to be present in some solid tumors." (PMID 31634348, 2019). "Notably, mutations in spliceosomal genes such as SF3B1, U2AF1, SRSF2, ZRSR2, and the RNA-stabilizing methyltransferase METTL3 are specifically enriched in haematological disease." (PMID 40495353, 2025). "Increased mitophagy is a therapeutic vulnerability in SRSF2-mutant hematologic malignancies." (PMID 38713535, 2024). "In addition to SF3B1, U2AF1, SRSF2, and ZRSR2, mutations in several spliceosome components have also been reported in both solid and hematologic malignancies, albeit at much lower frequencies." (PMID 37510283, 2023). "Since, in addition to SF3B1, mutations in U2AF1 and SRSF2 have also been observed in hematological malignancies, UM without a SF3B1 mutation—but with the characteristic chromosomal pattern—might harbor mutations in one of these genes." (PMID 31426461, 2019). "To address whether an increase in mitophagy is a feature of primary cells from patients with hematologic malignancies, we queried The Cancer Genome Atlas (TCGA) database for expression of markers of mitophagy in hematologic malignancies with or without the SRSF2 mutation." (PMID 38713535, 2024). "SRSF2 mutant MDS and AML PDX models showed a significant response to CTX-712, with many mice achieving complete remission, prompting the initiation of a currently ongoing multicenter, single-arm dose, phase I clinical trial for patients with hematologic malignancy (NCT05732103)." (PMID 37510283, 2023).
infection (13 papers, 2008 to 2021). The state of being infected such as from the introduction of a foreign agent such as serum, vaccine, antigenic substance or organism. "Immunofluorescence-based studies have demonstrated that SRSF2 retains its nuclear localization during infection with HRV14 or HRV16." (PMID 30142213, 2018). "Although a number of proteins appeared to re-equilibrate to the cytoplasm following infection with HRV16 in HeLa cells, there did appear to be some specificity in this process, insofar as SRSF2, for example, remained within the nucleus throughout infection." (PMID 30142213, 2018). "The distribution of SRSF2 was analyzed via immunofluorescence microscopy, and our results supported the nuclear retention of SRSF2 during HRV16 infection." (PMID 30142213, 2018). "Moreover, in the case of HIV, macrophages are an important viral reservoir, and it was found that HIV infection leads to an upregulation of the SR protein SRSF2 and a down‐regulation of hnRNP A/B and hnRNP H in the macrophages during the first weeks of infection." (PMID 31034770, 2019). "HPV replication is heavily dependent on the expression of some specific splicing factors, such as SRSF2 and SRSF3, at different times during infection." (PMID 31034770, 2019). "For example, two novel intergenic splicing events occurred between exons of SRSF2, JMJD6 and MXRA7 late in infection." (PMID 25989971, 2015). "Interestingly, however, in DENV2 infection, we determined small but significantly different changes in exon inclusion/exclusion levels in CHID1, SRSF2, HNRNPDL, and RBM39." (PMID 32380717, 2020).
haematological neoplasms (3 papers, 2019 to 2022). "In contrast to other haematological neoplasms, the presence of SRSF2 mutations has been consistently associated with an adverse prognosis in patients with SM, particularly among AdvSM cases." (PMID 35626091, 2022). "As one example, MPN18 harbored hematologic cancer-associated gene mutations in ASXL1, ETV6, and SRSF2 at baseline." (PMID 31911629, 2020).
neurodegenerative disease (3 papers, 2015 to 2021). A disorder of the central nervous system characterized by gradual and progressive loss of neural tissue and neurologic function. "Recently, however, the McKnight group demonstrated that SRSF2 does indeed form condensates in vitro, a hallmark feature of RBPs that aggregate in neurodegenerative disease, which importantly was reversible by phosphorylation." (PMID 34673031, 2021).
neurological diseases (2 papers, 2020 to 2022). "HNRNPDL and RBM39 function in transcriptional regulation, HNRNPDL and SRSF2 regulate alternative splicing, MPRIP is involved in stress granule formation, CHID1 has a role in pathogen sensing, and KIF21A has been implicated in neurological diseases." (PMID 32380717, 2020). "Indeed, identified genes are implicated in viral (SEC14L1, JMJD6, SRSF2, TMPRSS2, MX1, MX2) bacterial (COL8A1, SPIRE1), and neurological disorders (MFSD11, METTL23, CTTNBP2, BACE2, IMPA2, MPPE1 and GNAL), or in the functions of the Golgi complex (MGAT5B), organelle where viral envelope is occurred." (PMID 35581286, 2022).
liver (1 paper, 2020). "Taken together, loss of Srsf2 resulted in chronic liver injury, fibrosis and HCC development in mice." (PMID 32372053, 2020).
SRSF2 also shares sentences with these, for which no sentence is quoted: myeloproliferative neoplasm (10 papers); chronic neutrophilic leukemia (3); refractory anemia (3); acute lymphoblastic leukemia (2); cardiac hypertrophy (2); cutaneous melanoma (2); essential thrombocythemia (2); gastric tumors (2); mast cell leukaemia (2); polycythemia vera (2); prostate carcinoma (2); adenocarcinoma (1); Alzheimer disease (1); amyloid (1); amyotrophic lateral sclerosis (1); atherosclerosis (1); brain cancer (1); cancer of the eye (1); cardiovascular disorder (1); centronuclear myopathy (1); cholangiocarcinoma (1); chronic lymphoid leukemia (1); chronic myeloid leukemia (1); clear cell renal cell carcinomas (1); follicular lymphoma (1); head and neck cancer (1); hematological neoplasms (1); Herpes simplex infection (1); Holt-Oram syndrome (1); Huntington disease (1).
A further 31 diseases each share a sentence with SRSF2 in 1 paper.